CTLA4 (cytotoxic T-lymphocyte associated protein 4)
Diseases named in the same sentence as CTLA4 in open-access papers (continued):
Sharing a sentence is not in itself a finding about the gene and the disease.
melanoma (continued). "Nevertheless, mutations in B2M, which stabilize intracellular peptides on the cell surface and play a vital role in antigen presentation, were demonstrated to be associated with acquired resistance to CTLA-4 and PD-1 inhibitors in melanoma." (PMID 35087523, 2021). "Melanoma was the first FDA-approved indication for the use of cytotoxic T-lymphocyte-associated protein 4 (CTLA-4) inhibitor, ipilimumab." (PMID 34356899, 2021). "In melanoma, therapeutic targets include the T cell receptors, cytotoxic T-lymphocyte-associated antigen 4 (CTLA-4) and programmed cell death protein 1 (PD-1)." (PMID 34210290, 2021). "The antitumor effect of anti-CTLA-4 or anti-PD-L1/anti-PD-1 was significantly increased in IDO-deficient melanoma bearing mice." (PMID 34858835, 2021). "A Ctla4 promoter analysis in patients with colorectal cancer and melanoma has shown that CTLA-4 overexpression was caused by promoter hypomethylation." (PMID 34281195, 2021). "Further studies are also needed to elucidate the mechanisms underlying the clinical benefits of anti-CTLA-4 therapy in MAP2K1/2-mutated melanoma." (PMID 35069558, 2021). "For example, in a study of 26 melanoma patients treated with anti-CTLA-4, Firmicutes were associated with ICIs-induced colitis." (PMID 33692958, 2021). "In the present study, a logistic regression analysis showed that the use of anti-CTLA-4 inhibitor was an independent risk factor for ≥ grade 3 hepatotoxicity, and that a female sex and melanoma were confounding factors." (PMID 34046801, 2021). "Already there is one such phase III clinical trial success that has led to a marketed approval, i.e., the use of ipilimumab, the CTLA‐4 targeting antibody, for the treatment of postsurgical adjuvant high‐risk melanoma patients." (PMID 34125494, 2021). "The aim of this article is to study ILCs from peripheral blood of melanoma patients receiving Ipilimumab, an anti-CTLA-4 treatment, and their association with clinical responses to this therapy." (PMID 33810032, 2021). "Quezada and colleagues reported the presence of cytotoxic CD4 T cells and their importance to eradicate tumors in lymphopenic mice with melanoma, particularly in association with CTLA-4 blockade." (PMID 34064410, 2021). "In fact, CD155 expression on melanomas has also shown to be associated with a poorer response of metastatic melanoma patients to anti-PD-1 monotherapy and combination anti-PD-1 and CTLA-4." (PMID 33802954, 2021). "Specifically, this phylum was associated with a lower risk of developing colitis in melanoma patients treated with anti-CTLA-4 therapy." (PMID 34361904, 2021). "Monoclonal antibodies targeting the immune regulatory checkpoint receptors of anti-programmed cell death 1 (PD-1) and anti-cytotoxic T-lymphocyte-associated protein-4 (CTLA-4) have significantly improved the prognosis of patients with advanced melanoma." (PMID 34885249, 2021). "Programmed cell death-1 (PD-1), programmed cell death-1 ligand (PD-L1), and cytotoxic T-lymphocyte-associated antigen 4 (CTLA-4) therapies are effective in some patients with melanoma or non-small-cell lung cancer." (PMID 34917077, 2021). "A similar study in melanoma patients observed that high pre-therapy clonality was associated with poor response to CTLA4, whereas it predicted good response to PD1 blockade." (PMID 34899700, 2021). "Nonetheless, Ipilimumab (targeting Cytotoxic T-lymphocyte-associated protein 4 (CTLA-4)) showed an impressive improvement in overall survival in adult patients with advanced melanoma and became the first FDA approved immune checkpoint inhibitor in 2010." (PMID 35938052, 2021). "In other words, anti-CTLA-4 therapy was superior to anti-PD-1/L1 therapy for patients with MAP2K1/2-mutated melanoma." (PMID 35069558, 2021). "For example, Ipilimumab (Yervoy®), developed to inhibit CTLA-4 (cytotoxic T lymphocyte associated protein 4) expressed on T cells, is used in the treatment of advanced melanoma." (PMID 34205019, 2021).
melanoma (continued). "Pre-treatment PD-L1 expression on peripheral CD8+ and CD4+ T-cells was associated with worse outcome in melanoma patients receiving CTLA-4 blockade." (PMID 34071888, 2021). "Treatment of advanced melanoma with combined PD-1/CTLA-4 blockade commonly causes serious immune-mediated complications." (PMID 33664251, 2021). "We comprehensively curated pretreatment somatic mutational profiles and clinical information from 631 melanoma patients who received blockade therapy of immune checkpoints (i.e., CTLA-4, PD-1/PD-L1, or a combination)." (PMID 35087523, 2021). "Homozygosity in at least one HLA-I locus in patients treated with anti-CTLA-4, anti-PD-1, anti-PD-L1 or with a combination of ICIs for different types of cancer (mostly melanoma and NSCLC) is associated with shorter overall survival." (PMID 34680282, 2021). "Vitiligo is a commonly observed irAE with ICI treatment in patients with melanoma and it is more frequently associated with the use of PD-1 inhibitors (nivolumab and pembrolizumab) compared to the use of CTLA-4 inhibitors (ipilimumab)." (PMID 34358260, 2021). "Specifically for CD4+ T cells, elevated frequencies have been described to associate with longer OS in melanoma patients after Ipilimumab (anti-CTLA-4 Ab) therapy." (PMID 33546283, 2021). "Anti-CTLA-4 treatment was associated with longer OS in men only (HR = 0.77, p < 0.012) except for melanoma." (PMID 34769372, 2021). "In a previous study, 14% of patients with stage IV melanoma who received ipilimumab developed pruritic skin eruptions, with CTLA4 blockade believed to be the primary cause in eight of these patients." (PMID 33634154, 2021). "Different studies revealed the existence of an association between CTLA-4 gene polymorphisms and numerous cancers, for instance; melanoma, breast cancer, non-small cell lung cancer (NSCLC), skin cancer, gastric cancer, colorectal cancer, and many others." (PMID 35083014, 2021). "Approval in 2011 of the BRAF-inhibitor vemurafenib and the cytotoxic T-lymphocyte-associated protein 4 (CTLA-4)-antibody ipilimumab has resulted in significant improvements in the treatment of advanced melanoma." (PMID 33007949, 2020). "Cancer immunotherapy by immune-checkpoint inhibition (ICI) of the cytotoxic T-lymphocyte-associated Protein 4 (CTLA-4) and programmed cell death protein 1 (PD-1) and its ligand (PD-L1) has significantly improved the treatment of metastasized melanoma." (PMID 32290812, 2020). "Blocking antibodies of programmed death-1 (PD1) and cytotoxic T-lymphocyte–associated protein (CTLA-4) introduced a dramatic change in metastatic melanoma patients' treatment and prognosis, intensifying the proportion of responding melanoma patients." (PMID 32282861, 2020). "Drugs that target programmed cell death, including protein 1(PD1) and Cytotoxic T-lymphocyte-associated protein 4 (CTLA-4), have been effective in treatment of not only melanoma, but also other forms of lung cancers and Hodgkin lymphoma." (PMID 32235004, 2020). "Other research has demonstrated that baseline ALC was associated with longer OS in melanoma patients treated with ipilimumab, an anti-CTLA-4 antibody." (PMID 32133606, 2020). "Anti-CTLA-4 antibody is an immune checkpoint blocker associated with improved survival in melanoma patients having the high-affinity FcγRIIIa-V158 allele to IgG Fc relative to those carrying the low affinity allele, FcγRIIIa-F158." (PMID 32121592, 2020). "Ipilimumab (Yervoy®) is the first immune checkpoint agent, approved for the treatment of melanoma, which acts by blocking the cytotoxic T-lymphocyte-associated protein 4 (CTLA-4) and re-activating T cells." (PMID 34138136, 2020). "Tregs stained by FKBP51s are increased in melanoma patients and their counts are associated with anti-CTLA-4 response." (PMID 32317723, 2020).
melanoma (continued). "Low baseline lactate dehydrogenase (LDH) levels, high relative/absolute eosinophil counts, and relative lymphocyte counts were associated with prolonged OS in anti-PD-1 and CTLA-4 treated melanoma." (PMID 32864131, 2020). "The GLUT-ratio was higher in anti-PD1 responders than nonresponders (p = 0.08 for baseline; p = 0.02 for on-treatment) and associated with a progression-free survival in melanoma patients who treated with anti-CTLA4 (p = 0.04)." (PMID 32863946, 2020). "MAGE-A proteins, including three of the four genes identified in our analysis (MAGEA2, MAGEA3, and MAGEA6), have recently been implicated in resistance to CTLA-4 ICB in melanoma patients." (PMID 32117236, 2020). "The first clinical studies combining radiotherapy with ipilimumab (anti-CTLA-4-antibody; cytotoxic T-lymphocyte-associated protein 4) against prostate cancer and case reports in melanoma underline the significance of this clinical approach." (PMID 32340103, 2020). "For this reason, immune cells are the target of modern anti-melanoma therapy, directed mainly against programmed cell death protein 1 (PD-1) and cytotoxic T-lymphocyte associated protein 4 (CTLA-4)." (PMID 33171792, 2020). "Several of the CTAg genes detected in the CoMMpass analysis (MAGEA3, A6, A12, and CSAG1) were also in the CTAg gene set associated with resistance to anti-CTLA-4 therapy in melanoma." (PMID 32133047, 2020). "A further form of secondary autoimmune hypophysitis has recently been described in patients undergoing immunotherapy with antibodies to CTLA4 (cytotoxic T-lymphocytic-associated antigen-4) for melanoma or other malignancies." (PMID 32092880, 2020). "Retrospective analysis of an immunotherapy trial in melanoma also raised questions about association of high CRPs with suppression of responses against immunotherapy with anti‐CTLA4." (PMID 32027447, 2020). "A favorable association between anti-RANKL antibody denosumab and anti-CTLA-4 ipililumab was noted by chance in a case study of a melanoma patient co-administered these two drugs." (PMID 32443877, 2020). "High levels of CTLA4 were reported in B cell malignancies but also tumor-associated B cells in malignant melanoma." (PMID 32751214, 2020). "Depletion of Tregs was also associated with an improved efficacy of anti-CTLA-4 treatment combined with TLR1/2 (Toll-like receptor 1/2) ligands in the murine model of melanoma." (PMID 32517213, 2020). "In two different cohorts of melanoma patients treated with anti-CTLA-4, a significant association was observed between commensal microbiome composition and toxicity." (PMID 32671117, 2020). "Recently, some studies have indicated that increased tumor mutation loads were associated with survival benefit from both anti-CTLA-4 and anti-PD-1 therapy in multiple malignancies such as melanoma, lung cancer, and esophagogastric cancer." (PMID 33005180, 2020). "Two studies reported that lower baseline serum IL-6 was associated with irAEs in anti-CTLA-4 treated melanoma patients." (PMID 33643899, 2020). "Ipilimumab is an anti-cytotoxic T lymphocyte-associated protein 4 (CTLA-4) approved for the treatment of advanced melanoma and renal cell carcinoma and is also under clinical investigation in multiple adult and pediatric cancers." (PMID 33194646, 2020). "Responsiveness to CTLA-4 ICIs in melanoma was associated with higher overall kinase activity at baseline in responders when compared with non-responders, suggesting a generally more active immune system in responder patients." (PMID 33427690, 2020). "In melanoma, a higher expression of gene signatures related to T cell cytotoxicity was associated with the clinical activity of the anti-CTLA-4 ipilimumab." (PMID 32457745, 2020). "Nevertheless, its immunogenicity allows intervention via immunotherapeutic strategies such as cytotoxic T lymphocyte-associated antigen 4 (CTLA4) and programmed death-1 (PD-1) inhibitors, which are considered important for the treatment of malignant melanoma." (PMID 32964032, 2020).
melanoma (continued). "Concurrently, immune checkpoint inhibitors targeting Programmed Death -1 (PD-1) and cytotoxic T-lymphocyte associated protein 4 (CTLA-4) showed clinically significant improvements in OS in molecularly unselected populations of advanced melanoma patients." (PMID 32784823, 2020). "The outgrowth of Bacteroides fragilis was associated with the efficacy of CTLA-4 blockade in the treatment of melanoma patients with ipilimumab." (PMID 31594829, 2019). "It has been shown that high levels of chemokines CCL3, CCL4, and CXCL8 in pre-treatment tumor specimens were associated with worse patient overall survival after anti-CTLA4 and Carboplatin/paclitaxel treatment in melanoma." (PMID 30873179, 2019). "To understand how tumors escape anti-tumor immunity, we investigated tumor-associated T-cell repertoires of patients with advanced melanoma and after blockade of the cytotoxic T-lymphocyte-associated protein 4 (CTLA4) or programmed cell death 1 (PD-1)." (PMID 31275310, 2019). "Immunotherapy, such as cytotoxic T lymphocyte associated antigen 4 (CTLA4), programmed death-1 (PD-1) and programmed death ligand-1 (PD-L1) inhibitors, showed promising antitumor effects in malignant melanoma and non-small-cell lung carcinoma (NSCLC)." (PMID 30761122, 2019). "Monoclonal antibodies which specifically block CTLA-4, enhance effector T cells function and inhibit Tregs-associated immunosuppression have been demonstrated in murine models and melanoma patients." (PMID 31134073, 2019). "Decreases from baseline in melanoma patients, have been associated with improved responses to anti- CTLA-4 immunotherapy." (PMID 31395100, 2019). "New loci included common variants in BRCA2 (distinct to known rare high penetrance cancer risk variants), and in CTLA4, a target of immunotherapy in melanoma." (PMID 31174203, 2019). "Recently, major advancements have been achieved for metastatic melanomas via the blockade of immune-checkpoints using a programmed death 1 (PD-1) checkpoint inhibitor and a cytotoxic T-lymphocyte-associated antigen 4 (CTLA-4) checkpoint inhibitor." (PMID 30719233, 2019). "It targets a checkpoint molecule known as cytotoxic T lymphocyte associated protein-4 (CTLA-4) and was approved for the management of melanoma." (PMID 31366131, 2019). "For example, cytotoxic T-lymphocyte associated antigen 4 antibody (CTLA-4 Ab) can inhibit checkpoint receptor and has been used in patients with melanoma." (PMID 31119124, 2019). "Blockade of cytotoxic T-lymphocyte-associated antigen 4 (CTLA-4) using the antagonistic monoclonal antibody (mAb) ipilimumab was the first strategy to achieve a significant clinical benefit for stage IV melanoma patients." (PMID 31462642, 2019). "The success of ipilimumab, which is an anti-cytotoxic T-lymphocyte-associated protein 4 (CTLA-4) monoclonal antibody (mAb), in the treatment of advanced melanoma started a new era of immune checkpoint inhibitors (ICIs) in systemic anti-cancer treatment." (PMID 31718585, 2019). "High levels of soluble PD-L1 in sera of patients with melanoma prior to immune checkpoint therapy were associated with increased likelihood of progressive disease after treatment with CTLA-4 blocking antibodies." (PMID 30564891, 2019). "We present phase 1 results from a phase 1/2 clinical study of epacadostat in combination with ipilimumab, an anti-cytotoxic T-lymphocyte-associated protein 4 antibody, in advanced melanoma (NCT01604889)." (PMID 30894212, 2019). "Several lines of evidence have underlined the role of PTEN loss on melanoma progression and resistance to immunotherapy management in patients sequentially treated with anti-Cytotoxic T-Lymphocyte Antigen 4 (CTLA-4) and anti PD-1 agents." (PMID 31500143, 2019). "Another study involving patients with melanoma showed that mutations in either SERPINB3 or SERPINB4 were correlated with significantly longer survival following anti-CTLA4 treatment." (PMID 31277279, 2019).
melanoma (continued). "Antibodies directed against the cytotoxic T-lymphocyte-associated antigen 4 (CTLA-4) receptor or programmed cell death-1 (PD-1) receptor have revolutionized the systemic therapy of advanced melanoma." (PMID 31506076, 2019). "Actually, tumor-intrinsic, active β-catenin signaling in human melanoma causes resistance to monoclonal antibodies including anti-PD-L1and anti-CTLA4 via T cell exclusion." (PMID 31616443, 2019). "They appear in 85% of melanoma patients treated with cytotoxic T-lymphocyte-associated protein 4 (CTLA-4) antibody ipilimumab and even with a delay of several months after treatment." (PMID 30171420, 2018). "The attenuated strains of measles virus (MV) encoding antibodies against CTLA-4 and PD-L1 (MV-aCTLA-4 and MV-aPD-L1) have been generated and tested in an immunocompetent murine model of malignant melanoma to evaluate the therapeutic efficacy of the virus." (PMID 29857493, 2018). "In melanoma patients, increase in tumor infiltrating lymphocytes (TILs) 3 weeks after treatment with anti-CTLA-4 was associated with clinical activity." (PMID 29968076, 2018). "The success of cytotoxic T lymphocyte-associated protein 4 (CTLA-4) antibodies in the treatment of early melanoma introduced immune checkpoint molecules as emerging targets for immunotherapy." (PMID 30309387, 2018). "The first reports on this issue have addressed the correlation between the mutational burden and the clinical benefit from anti-CTLA4 blockade in melanoma patients." (PMID 30060457, 2018). "Pertinent to this concept, a recent report of melanoma patients treated with combination CTLA-4 and PD-1 blockade associated their risk of developing immune-related adverse events with the expansion of CD21lo B cells with a nonlymphoid tissue–homing profile." (PMID 30091725, 2018). "For example, attenuated measles virus (MV) vectors that encode CTLA-4 and PD-L1 antibodies can improve therapeutic outcomes in murine models of malignant melanoma and reduce tumor size." (PMID 29735917, 2018). "Given its mechanism and clinical benefit in melanoma, trials involving dual blockade with PD-1/PD-L1 and cytotoxic T-lymphocyte-associated protein 4 inhibitors in sarcoma are ongoing (NCT02428192, NCT02982486)." (PMID 30545340, 2018). "In contrast, maintenance of high-frequency TCR clonotypes alongside CTLA-4 blockade therapy was associated with improved overall survival in prostate cancer and melanoma." (PMID 29403496, 2018). "Anti-CTLA-4 use was associated with longer OS in men only (HR 0.77, p < 0.012), with the exception of melanoma (in women, HR 0.80, p = 0.006)." (PMID 30545122, 2018). "Clinical validation of the predictive role of aneuploidy in melanoma patients treated with anti–CTLA-4 revealed that high SCNA levels were associated with a poorer response." (PMID 29385739, 2018). "Although we only profiled two such cases and larger cohorts are needed, a low point mutation burden relative to human sun-exposed melanoma has potential bearing on expected responses to immunotherapy such as anti-CTLA4 and anti-PD1 checkpoint blockade." (PMID 30188888, 2018). "This has been demonstrated for lung cancer patients treated with anti-PD-1 therapy, melanoma patients treated with anti-CTLA-4, and patients with mismatch repair deficient tumors across several cancer types with anti-PD-1 treatment." (PMID 30285902, 2018). "Inhibition of T cell checkpoint molecules such as cytotoxic T-lymphocyte-associated antigen-4 (CTLA-4) and programmed cell dealth-1 (PD-1) using monoclonal antibodies has achieved remarkable success in cancer treatment including melanoma in humans." (PMID 29385676, 2018). "RT-PCR was performed for 169 genes associated with inflammation, immunity, CTLA-4 pathway and melanoma." (PMID 30227886, 2018).